TGFB1 (transforming growth factor beta 1)
Diseases named in the same sentence as TGFB1 in open-access papers (continued):
Sharing a sentence is not in itself a finding about the gene and the disease.
hepatocellular carcinoma (continued). "Our studies demonstrated that hMSC and TGFβ-1 gene infected hMSC can promote the different metastatic potential hepatoma cells proliferation and inhibit different metastatic potential hepatoma cells migration." (PMID 26003220, 2015). "So, it is to observe the changes of proliferation and metastasis ability, which the high expression TGFβ-1 of hMSC by gene modified technology is on the different metastatic potential hepatoma cells and xenograft models." (PMID 26003220, 2015). "Hep3B cell line, which is derived from human hepatocellular carcinoma cells, has been reported to be sensitive to TGFβ1, and the cell growth of Hep3B was inhibited by treatment with TGFβ1." (PMID 25826092, 2015). "In the present study, we demonstrate that the growth of the murine Lewis lung carcinoma (LLC) and human hepatocellular carcinoma Hep3B cell lines was suppressed by stimulation with TGFβ1." (PMID 25826092, 2015). "OPN gene relative quantitative expression of hepatoma cells was significantly down-regulated after co-cultured with hMSC and TGFβ-1 gene infected hMSC groups (P < 0.05)." (PMID 26003220, 2015). "The mice were engrafted with hMSC and TGFβ-1 gene infected hMSC, respectively, after hepatoma cells inoculation 15 days, twice a week for 6 weeks successively." (PMID 26003220, 2015). "The two hepatoma cells were co-cultured with hMSC and TGFβ-1 infected hMSC, respectively, and hepatoma cells with culture medium acted as the control groups." (PMID 26003220, 2015). "hMSC and TGFβ-1 gene infected hMSC can promote hepatoma cells proliferation and inhibit hepatoma cells migration." (PMID 26003220, 2015). "The migration numbers of hepatoma cells with TGFβ-1 infected hMSC co-culture groups were significantly reduced compared with the other two groups (P < 0.05)." (PMID 26003220, 2015). "TGFβ-1 infected hMSC or hMSC co-culture with hepatoma cells groups can significantly promote hepatoma cells proliferation (P < 0.05)." (PMID 26003220, 2015). "The hMSC and transforming growth factor-β1 (TGFβ-1) gene infected hMSC were co-cultured with hepatoma cells." (PMID 26003220, 2015). "Pro-TGFβ1 is a substrate of furin, of which the active form (TGFβ1) suppresses the growth of Hep3B and Huh7 hepatoma cells." (PMID 22808247, 2012). "PDCD4 was suggested to be a proapoptotic molecule involved in transforming growth factor beta-1 (TGF beta-1) induced apoptosis in hepatocellular carcinoma (HCC)." (PMID 22272332, 2012). "Thrombospondin-1 (THBS1; upregulated in POAG LC cells) is a major activator of extracellular transforming growth factor beta 1 (TGFβ1) in fibrotic renal disease in the rat and is closely involved in angiogenesis in hepatocellular carcinoma." (PMID 19145252, 2009). "Mesenchymal CD90-positive hepatoma cells have been suggested to be produced by TGFb1 treatment." (PMID 40253402, 2025). "In addition, the JUNB expression in EpCAM-positive hepatoma cells was increased by paracrine stimulation with fibroblast-derived TGFb1." (PMID 40253402, 2025). "Previous studies showed that ITGIBL1 protein could promote migration and invasion in hepatocellular carcinoma cells by stimulating the TGFβ/SMAD signalling pathway through interaction with TGFβ1." (PMID 35733144, 2022). "Indeed, the Huang team observed that lncRNA TP73-AS1 axis was repressing the miR-539 expression, promoting MMP-8 expression, and activating TGFβ1 signaling to induce M2 macrophage polarization in hepatocellular carcinoma." (PMID 36497429, 2022).
hepatocellular carcinoma (continued). "For example, TGFβ-1 treatment of hepatocellular carcinoma cells and osteoarthritic fibroblasts leads to increased expression of specific cross-linking enzymes from the LOXL and LH families, while similar treatment of dermal fibroblasts increased the expression and activity of TG2." (PMID 33498156, 2021). "This method could detect transforming growth factor beta 1 (TGF-β1), a secreted protein involved in cell proliferation as well as a biomarker of hepatocellular carcinoma." (PMID 34947888, 2021). "Interestingly, mainly Tgfb1 and Spp1 mRNA are highly overexpressed in the hepatoma cells with respect to the levels observed in normal fresh hepatocytes." (PMID 34737944, 2021). "Promotes EMT and invasiveness of hepatocellular carcinoma through TGFβ1 autoregulation circuitry." (PMID 28228731, 2017). "The aim of this study was to test the causal association between circulating transforming growth factor beta 1 (protein: TGF-β1 and coding gene: TGFB1) and hepatocellular carcinoma by choosing TGFB1 gene C-509T polymorphism as an instrument in a Mendelian randomization (MR) meta-analysis." (PMID 27835897, 2016). "Indeed, qPCR results showed that hepatoma cells expression TGFβ-1 in gene infected hMSC and hMSC groups were higher than in control groups." (PMID 26003220, 2015). "However, we still do not know exogenous TGFβ-1 (by TGFβ-1 gene infected hMSC expression) or endogenous TGFβ-1 (by hepatoma cells expression) the differences of the biological mechanism in promoting hepatoma cells proliferation." (PMID 26003220, 2015). "In addition to LLC cells, we also demonstrated that TGFβ1-mediated cell growth suppression was enhanced by LRG in human hepatoma Hep3B cells, which have been reported to be sensitive to TGFβ1-mediated cell growth suppression, resulting in apoptosis." (PMID 25826092, 2015). "It is worth mentioning that OPN expression down-regulated after hepatoma cells were co-cultured with hMSC and TGFβ-1 gene infected hMSC and may be used to explain metastatic potential decrease." (PMID 26003220, 2015). "hMSC and TGFβ-1 infected hMSC co-culture with hepatoma cells groups served as experimental groups." (PMID 26003220, 2015). "The dual role of TGFβ1 may explain our observations that furin enhances hepatoma cell invasiveness in the tail vein xenograft model, while suppresses tumor growth in the subcutaneous xenograft model." (PMID 22808247, 2012). "Furthermore, IL-4 and transforming growth factor beta-1 (TGF-β1) have been demonstrated to suppress HBV replication in hepatoma cells through the transcriptional regulation of HBV RNA." (PMID 19374779, 2009). "Overall, these results indicate that the knockdown of CAPG reverses Dox resistance by inducing ferroptosis through the TGFB1/Nrf2 signalling pathway in hepatocellular carcinoma (HCC) cells." (PMID 40982354, 2025). "HOXB9 functions as a transcriptional activator and induces TGFβ1 in hepatocellular carcinoma (HCC) cells, enhancing their migratory and invasive potential." (PMID 34617205, 2022). "TTP has also been shown to be downregulated in hepatocellular carcinoma (HCC) cells and tumors through an epigenetic mechanism that involves hypermethylation of a single CpG site within the TGFβ1 responsive region of the TTP promoter." (PMID 32545247, 2020). "Furthermore, it has been shown that TGFβ1 up-regulates miR-155 in hepatocellular carcinoma cells, thus promoting epithelium-to-mesenchyme transition, invasion and metastasis, and that miR-155 plays a role in mediating TGFβ1-induced podocyte injury via nephrin, desmin and caspase-9." (PMID 29987196, 2018). "Also, similar tendency was observed in TGFβ1-treated hepatocellular cancer HepG2 cells." (PMID 25837484, 2015). "Transforming growth factor β1 (TGFβ1) is identified to be capable of up-regulating CD133 expression specifically within the Huh-7 hepatocellular carcinoma (HCC) cell line in a time- and dose-dependent manner." (PMID 23815814, 2013).
hepatocellular carcinoma (continued). "Besides growth inhibition, TGFβ1 also induced apoptosis in hepatoma cell." (PMID 22808247, 2012). "In vitro, we used co-cultures of human hepatocellular carcinoma cell line (HepG2) and human hepatic stellate cell line (LX-2) cells transfected using an SHBG expression vector vs. vehicle and treated with transforming growth factor beta 1 (TGF-β1)." (PMID 42278422, 2026). "Scientists have shown that TGFβ1 inhibits DNMT1 and DNMT3β in hepatocellular carcinoma, which led to overexpression of CD133 in the cells by demethylation of CD133 promoter-1." (PMID 34051847, 2021). "TAMs are negatively correlated with the survival of hepatocellular carcinoma (HCC) patients, since these TAMs secrete TGFβ1 to induce the EMT and confer higher invasiveness in cancer cells." (PMID 36046433, 2021). "HDAC1 is also required for TGFβ1-induced EMT in hepatocytes and frequently overexpressed in hepatocellular carcinoma (HCC), suggesting a strong connection between HDAC1 and the invasive properties of HCC." (PMID 26905733, 2016). "Therefore, in order to investigate intervention effects of hMSC to hepatocellular carcinoma tissue, in this study, TGFβ-1 was infected into human bone marrow-derived mesenchymal stem cells using a transgenic technology based on the biological characteristics of TGFβ-1." (PMID 26003220, 2015). "MHCC97-H and MHCC97-L cells served as control groups, and osteopontin (OPN), TGFβ-1, and programmed cell death protein 4 (PDCD4) gene expression levels in hepatoma cells was set as 100 %." (PMID 26003220, 2015). "Transforming growth factor beta 1 (TGF-β1), a liver fibrosis-inducing factor, was highly expressed in the alcohol-fed group and human hepatoma HepG2 cell; however, the increase in TGF-β1 expression was reduced following fucoidan administration." (PMID 25690093, 2015). "TGFβ-1, osteopontin (OPN), and programmed cell death protein 4 (PDCD4) genes expression of hepatoma cells were detected by quantitative real-time polymerase chain reaction (qPCR) before and after co-cultured experiments." (PMID 26003220, 2015). "In addition, childhood Hepatocellular Carcinoma related genes SPP1 and TGFB1 were also strongly expressed in the endothelial and megakaryocyte." (PMID 34095116, 2021). "Indeed, TGFβ1 is a known transcriptional inhibitor of DCN gene, and the hepatoma cell lines applied produce considerable amounts of the cytokine." (PMID 32477937, 2020). "In the current study, our results showed that JR pretreatment partly blocked TGFβ1-induced phosphorylation of Smad2/3, indicating JR may inhibit TGFβ1-induced EMT in hepatoma cells through Smad2/3-dependent pathway." (PMID 30174709, 2018). "So, we can draw a conclusion that the hMSC of infected TGFβ-1 gene can more obviously promote the hepatoma cells proliferation and does not affect the hepatoma cells apoptosis." (PMID 26003220, 2015). "Several cancer types, including basal cell carcinoma, hepatocellular carcinoma, non-small cell lung cancer, cutaneous squamous cell carcinoma, and solid tumors, share two common targets: prostaglandin-endoperoxide synthase 2 (PTGS2) and transforming growth factor beta 1 (TGFB1)." (PMID 41041638, 2025). "TAMs can enhance the CSC-like phenotype via TGFB1, which induces EMT program activation in a hepatocellular carcinoma (HCC)." (PMID 39981232, 2025). "The study reveals that TGFB1, E2F1, and HMBS could potentially serve as markers to identify the activation of the hepatic fibrosis signaling pathway and its corresponding biological function in the development of hepatocellular carcinoma." (PMID 38068980, 2023). "Meanwhile, the endogenous expression of TGFβ1 was tightly mediated by MMP-7, thus constituting an MMP-7/syndecan-1/TGFβ1 autocrine loop to mediate hepatocellular carcinoma (HCC) metastasis." (PMID 31822964, 2020).
hepatocellular carcinoma (continued). "The present study also showed that JR has the ability to inhibit the activation of Akt, ERK, JNK and p38 MAPK, suggesting that JR may suppress TGFβ1-induced EMT expression and thereby migration and invasion of hepatoma cells via Smad-dependent and Smad-independent pathways." (PMID 30174709, 2018). "ID1 is also reported to be involved in TGFβ1-induced EMT activation, thus enhancing tumor progression in human cancer cells; while inactivation of ID1 by inhibiting ID1 expression via berberine has potential therapeutic value against primary and metastatic growth of hepatocellular cancer." (PMID 28611292, 2017). "While TGFβ1 mediated activation of STAT3 in skeletal muscles was not reported previously, TGFβ1 activated STAT3 by phosphorylating Tyr705 has been reported in hepatic cells and a mouse model of hepatocellular carcinoma." (PMID 26380299, 2015). "Further, from the TGFβ-1 and PDCD4 gene expression by qPCR method, test results showed hMSC promoted hepatoma cells proliferation but had no obvious effect on hepatoma cells apoptosis." (PMID 26003220, 2015).
fibrosis (871 papers, 2005 to 2026). the formation of excess fibrous connective tissue in an organ or tissue in a reparative or reactive process. "In the current study, the findings reveal increased ROS stress associated with Tgfb1-centered pro-fibrotic network in the bleomycin-induced lung injury and fibrosis mouse model." (PMID 40978478, 2025). "Cardiac fibrosis is a relevant hallmark of pathological hypertrophy and the gene Tgfb1 is one of its preeminent markers." (PMID 36695670, 2023). "Transforming growth factor-beta 1 (TGF-β1) is widely implicated in fibrotic diseases including Dupuytren’s disease (DD; also known as palmar fascia fibrosis)." (PMID 30927912, 2019). "By establishing TGFβ1-induced oral submucosa fibroblast fibrosis model, we evaluated the function and the underlying mechanism of PTMA in OSF." (PMID 29088825, 2017). "The TGFβ1 (C-509T) polymorphism was significantly associated with an increased risk of fibrosis, whereas the XRCC1 (R399Q) polymorphism was significantly associated with an increased risk of telangiectasia." (PMID 17325707, 2007). "Fibrosis risk is associated with an inflammatory response (an acute reaction and/or TGFβ1), whereas telangiectasia is associated with vascular endothelial cell damage (boost and/or XRCC1)." (PMID 17325707, 2007). "Although increased cardiac fibrosis is a hallmark of structural remodelling in response to a diabetic environment, we paradoxically found decreased collagen deposition along with decreased expression of Tgfb1 in both Hif1a+/− and Wt diabetes-exposed LV at 12 weeks of age." (PMID 29753320, 2018). "In particular, we investigated the involvement of transforming growth factor-beta 1 (TGF-β1), a multifunctional cytokine that plays an important role in cardiac fibrosis, wound, and tissue repair, and its relationship with SNRK." (PMID 40584789, 2025). "Here, our analysis using human dural fibroblasts—a cellular model that enhances the translational relevance to humans—also revealed TGFβ1, a well-known pro-fibrotic cytokine, as a key mediator of dural fibrosis." (PMID 40247257, 2025). "Fibrosis of the conjunctiva is primarily mediated by mast cells, growth factors such as TGFβ1, and M2-like macrophages, elements that also play central roles in skin fibrosis." (PMID 41223193, 2025). "Sensitive to small variations in TGFβ1, our model reproduces the collagen accumulation observed in these different fibrosis mouse models." (PMID 39074160, 2024). "We first examined the alterations in collagen and FGF13 expressions in a TGFβ1-induced fibrosis modelin vitro." (PMID 38818580, 2024). "Using a well-established in vitro fibrosis model, we stimulated primary human skin FBs with TGFβ1 and investigated the effect of PBMCsec on myofibroblast (myoFB) formation." (PMID 37111549, 2023). "The results of our fibrosis PCR array also showed a slight increase in the expression of TGFB1 (1.7-fold) in untreated cells." (PMID 37235555, 2023). "Expression of TGFβ1, IL-11 and IL-6, mediators involved in cardiovascular fibrosis and inflammation, were increased in hearts from TRPM7-deficient mice and aldosterone-salt treated WT mice." (PMID 35882956, 2022). "Injection of MANPs incorporating TGFβ1-siRNA (TGFβ-siRNA-MANPs) 5 d after the induction of bleomycin-induced fibrosis significantly reduced disease severity." (PMID 35377803, 2022). "In this study, we provide new insights into the anti-fibrotic mechanisms of pirfenidone and nintedanib and uncover novel drug targets in TGFβ1-driven fibrosis." (PMID 35197532, 2022). "Fibrosis regression occurred despite high expression of the canonical pro-fibrogenic cytokine Tgfb1 and, in some cases, the pro-inflammatory cytokines Il6 and Tnf, which have frequently been shown to diminish in the resolution phase of disease." (PMID 35169835, 2022).